CXCL13 (C-X-C motif chemokine ligand 13)
Diseases named in the same sentence as CXCL13 in open-access papers (continued):
Sharing a sentence is not in itself a finding about the gene and the disease.
Lyme neuroborreliosis (continued). "This review demonstrates that the presence of CXCL13 in CSF is not unique to neuroborreliosis or neurosyphilis." (PMID 32331231, 2020). "It should be noted that CXCL13 is not specific to Lyme neuroborreliosis; increased CSF values have also been found with neurosyphilis, tubercular meningitis and CNS lymphomas." (PMID 32341686, 2020). "Intrathecal production of CXCL13 was found decreased in patients with non-inflammatory neurological conditions, high in patients with Lyme neuroborreliosis (>250 pg./mL) and moderate high in patients with MS who had focal dysfunction of the blood-CSF barrier (5–100 pg.//mL)." (PMID 40165834, 2025). "However, determining levels of CXCL13 as a marker for LNB can aid in the diagnosis but should be interpreted with care since CXCL13 has been reported to be nonspecific to Lyme neuroborreliosis." (PMID 37528399, 2023). "CXCL13 is not expressed in the CNS in physiological conditions, but its expression is high in the brain and spinal cord under pathological conditions, such as autoimmune demyelination, primary CNS lymphoma, and Lyme neuroborreliosis (LMN)." (PMID 35892669, 2022). "However, CXCL13 is not specific for Lyme neuroborreliosis and can also be found in some other inflammatory diseases of the CNS." (PMID 32793606, 2020). "However, CSF CXCL13 (a B-cell-attracting chemokine) was, as in 11 other TBE cases in this cohort (n = 12, median 32 pg/mL, range 14–240 pg/mL), below the cut-off shown earlier by us to differentiate between neuroborreliosis and other inflammatory CNS diseases." (PMID 32992967, 2020). "In early neuroborreliosis, the chemokine CXCL13 may be of value as high levels may be seen in the CSF of untreated patients with neuroborreliosis when antibody titers have not yet risen." (PMID 33324914, 2020). "However, the study also demonstrated that elevation of CXCL13 is not specific for neuroborreliosis but is also present in neurosyphilis, cryptococcal meningitis, and primary/secondary B-cell lymphoma, suggesting the need for careful interpretation of results in this context." (PMID 38674602, 2024). "In addition, CXCL13 measurements in the blood are not specific to neuroborreliosis and neurosyphilis patients, since CXCL13 concentrations in healthy individuals and other CNS disorders are often comparable to those in subjects with neuroborreliosis and neurosyphilis." (PMID 32331231, 2020). "CXCL13 participates in TLS formation in some autoimmune diseases, such as primary Sjögren’s syndrome, systemic lupus erythematosus, myasthenia gravis, and atherosclerosis, but not in rheumatoid arthritis or acute Lyme neuroborreliosis." (PMID 34947813, 2021).
rheumatoid arthritis (61 papers, 2012 to 2026). A chronic, systemic autoimmune disorder characterized by inflammation in the synovial membranes and articular surfaces. "CXCL13 has also been suggested to play a pathogenic role in inflammatory disorders, such as rheumatoid arthritis and inflammatory bowel disease." (PMID 38880863, 2024). "CXCL13 has also been identified in the serum of patients with rheumatoid arthritis where it is associated with active disease." (PMID 30092845, 2018). "Monocytes and macrophages also secrete CXCL13 in TLOs associated with rheumatoid arthritis and ulcerative colitis, providing a rich source of lymphoid chemokines in chronic inflammation." (PMID 29218052, 2017). "We here examine the role of CXCL13 and its association with disease in patients with treatment-naïve early rheumatoid arthritis." (PMID 25249397, 2014). "In treatment-naïve early rheumatoid arthritis patients, plasma CXCL13 levels were associated with joint inflammation." (PMID 25249397, 2014). "CXCL13 is found in TLOs, including those associated with Helicobacter pylori, rheumatoid arthritis, Sjögren’s syndrome, inflammatory transgenes, and cancer." (PMID 23230435, 2012). "Of note, cluster 3 failed to express the subset of Tph-associated chemokines (e.g., Cxcl13, Ccr2, Cx3cr1) described in rheumatoid arthritis and other conditions, a finding consistent with previous reports that chemokine expression by Tph cells is context dependent." (PMID 39087473, 2024). "Moreover, macrophages represent a potent inducible source of CXCL13 in chronic inflammatory diseases associated with formation of T‐ and B‐cell aggregates, such as rheumatoid arthritis and ulcerative colitis, where they possibly play a role in the genesis of the lymphoid tissue." (PMID 32452646, 2020). "The CXCL10/CXCR3 and CXCL13/CXCR5 axes are associated with disease activity in several autoimmune diseases including rheumatoid arthritis (RA), systemic lupus erythematosus (SLE) and adult onset Still’s disease." (PMID 29116188, 2017). "However, although FDCs are a major source of CXCL13 in LNs, monocytes and macrophages have also been shown to secrete this chemokine in the TLOs associated with rheumatoid arthritis and ulcerative colitis, suggesting additional chemokine sources in chronic inflammation, including LTo cells." (PMID 23230435, 2012). "The factors driving TLS generation are complex; for example, fibroblasts in the tissues of rheumatoid arthritis produce lymphochemokines such as CXCL13, CCL19, and CCL21, which are involved in TLS formation." (PMID 40718780, 2025). "Serum CXCL13 was found to be increased with several systemic active diseases such as rheumatoid arthritis, systemic lupus erythematosus, and infections." (PMID 39857624, 2024). "In rheumatoid arthritis, CXCL13 is highly produced by PD-1hiCXCR5–CD4+ T cells in the synovium, which are different from Tfh cells." (PMID 37815865, 2023). "Other researches showed that CXCL10 was recommended as a disease activity marker of early rheumatoid arthritis, as well as serum CXCL13 level was closely related to rheumatoid arthritis and rheumatoid factor levels." (PMID 37393391, 2023). "As reported in rheumatoid arthritis, proinflammatory cytokines enhance secondary CXCL13 production by reactivating CXCL13-producing CD4 T cells." (PMID 35734177, 2022). "Another caveat is that CXCL13 expression is altered in response to infection, in cancer, systemic lupus erythematosus, rheumatoid arthritis, and other diseases involving germinal center, or ectopic lymphoid structure formation." (PMID 35211125, 2022). "We evaluated the differential expression of CXCL13 in the 88 iMCD patient samples in the Primary cohort compared to 20 rheumatoid arthritis (RA) patients, 20 Hodgkin lymphoma (HL) patients, and 20 HHV8-associated MCD (HHV8-MCD) patients." (PMID 36433996, 2022).
rheumatoid arthritis (continued). "CXCL13 neutralizing monoclonal antibody significantly reduced disease severity in animal models of rheumatoid arthritis and experimental autoimmune encephalomyelitis." (PMID 34869409, 2021). "A study showed that spebrutinib (CC-292), a small molecular inhibitor of Bruton’s tyrosine kinase (BTK), significantly reduces the serum concentration of CXCL13 and shows a therapeutic effect on rheumatoid arthritis." (PMID 34947813, 2021). "In murine collagen-induced arthritis, a model of rheumatoid arthritis, blocking CXCL13 reduced disease severity and decreased synovial germinal center formation." (PMID 34868008, 2021). "SOX-4–mediated CXCL13 production by CD4 T cells is involved in the formation of ectopic lymphoid-like structures (TLSs) in rheumatoid arthritis." (PMID 33332284, 2021). "A study conducted in rheumatoid arthritis (RA) patients showed that CXCL13 produced by follicular dendritic cells (FDCs) attracted B cells to the tertiary lymphoid follicles of the inflammatory sites." (PMID 33732259, 2021). "Here the authors show that a transcription factor, Sox4, induces the expression of CXCL13 in CD4 T cells in vitro, and is associated with ELS formation in patients with rheumatoid arthritis." (PMID 30232328, 2018). "In the present study we investigated the role of the CXCL13/CXCR5 axis in the pathogenesis of rheumatoid arthritis (RA) and specifically addressed the impact of CXCR5-mediated T and B cell migration in this disease." (PMID 28827539, 2017). "As reported in rheumatoid arthritis, proinflammatory cytokines enhance secondary CXCL13 production from reactivated CXCL13‐producing CD4+ T cells." (PMID 26541894, 2016). "Baseline CXCL13 plasma levels were increased in early rheumatoid arthritis patients in comparison with healthy volunteers." (PMID 25249397, 2014). "In the synovial tissues of rheumatoid arthritis, CXCL13 is produced by PD-1hiCXCR5−CD4+ T cells." (PMID 34947813, 2021). "CXCL13/CXCR5 axis also facilitates angiogenesis during rheumatoid arthritis progression." (PMID 34947813, 2021). "A CXCL13‐producing CD4 T‐cell subset was reported in rheumatoid arthritis." (PMID 33943020, 2021). "Indeed, strong overexpression of CXCL13 mRNA and protein was found in the synovia of patients with rheumatoid arthritis, particularly in the regions of B-cell aggregation." (PMID 31354634, 2019). "Moreover, statistically significant correlation between IL-17 and CXCL13 levels in synovial fluid of patients with rheumatoid arthritis has been observed." (PMID 25879435, 2015). "Circulating levels of CXCL13 (C-X-C motif chemokine 13), a chemokine known to attract B cells, are elevated, correlate with disease activity, severity and treatment response in patients with SLE, Sjögren’s syndrome, rheumatoid arthritis and ANCA-associated vasculitides." (PMID 35967377, 2022). "The B cell chemoattractant CXCL13 is a promising biomarker in rheumatoid arthritis (RA), with a plausible role in supporting diagnosis, monitoring disease activity and as a prognostic value." (PMID 33292827, 2020). "These cells were first detected in the synovial fluid and tissue of patients with rheumatoid arthritis (RA) patients, and phenotypically resemble Tfh, in particular through the secretion of IL‐21, a central cytokine for B‐cell differentiation and CXCL13, a B‐cell chemoattractant." (PMID 40538220, 2025). "In one of the early studies on CXCL13 expression in the developing lymphoid tissues of patients with rheumatoid arthritis (RA) and ulcerative colitis (UC), macrophages and activated monocytes were found to be the main sources of CXCL13 in the tissues where TLSs were formed." (PMID 39355243, 2024). "The CXCL13/CXCR5 axis facilitates endothelial progenitor cell homing and angiogenesis during rheumatoid arthritis progression." (PMID 36739468, 2023). "CXCL13, CCL21, and CXCL12, were also found in chronic inflammatory diseases, including SS, rheumatoid arthritis, and other disease models." (PMID 31921189, 2019).
rheumatoid arthritis (continued). "In the ectopic lymphoid‐like structures present in chronic inflammatory conditions such as rheumatoid arthritis, a subset of human effector memory CD4+ T cells that lacks features of follicular helper T (Tfh) cells produces CXCL13." (PMID 26541894, 2016). "Particular attention is given to the PD-1hi CXCR5− Bcl6low T peripheral helper (Tph) cell population in rheumatoid arthritis, which infiltrates inflamed synovium through expression of chemokine receptors such as CCR2 and augments synovial B cell responses via CXCL13 and IL-21." (PMID 30190721, 2018). "It has also been found that Cxcl13 mRNA levels are elevated in synovial tissues from rheumatoid arthritis patients, but not in osteoarthritic joints." (PMID 24967215, 2014). "We hypothesized that serum levels of C-X-C motif chemokine 13 (CXCL13), a B-cell chemokine, would delineate a subset of rheumatoid arthritis (RA) patients characterized by increased humoral immunity." (PMID 24766912, 2014).
ovarian carcinoma (59 papers, 2013 to 2025). A malignant neoplasm originating from the surface ovarian epithelium. "In ovarian cancer, high CXCL13 expression is associated with prolonged survival by shaping the anti-TME by facilitating the maintenance of CXCR5+CD8+ T cells." (PMID 40406143, 2025). "CXCL13, for example, has been identified as a prognostic factor in ovarian cancer owing to its association with the number of tumor-infiltrating lymphocytes." (PMID 37284314, 2023). "Conclusively, anti-PD-1 combined with CXCL13 treatment is associated with a better treatment response than anti-PD-1 alone in a mouse model of ovarian cancer." (PMID 35053457, 2022). "In this study, we found that CXCL13 gene expression was a prognostic factor for ovarian cancer and was associated with the presence of TLS." (PMID 35552285, 2022). "CXCL13 expression itself associated with prognosis, immune infiltration, and T cell exhaustion in ovarian cancer." (PMID 36341460, 2022). "CD6, CXCL9, and CXCL13 were associated with favorable outcomes in BRCA1-mutant ovarian cancers." (PMID 40647506, 2025). "In ovarian cancer an increased frequency of CD103+ CD8+ T cells expressing CXCL13 is associated with increased B cell density further suggesting an important role for CXCL13 producing T cells in driving B cell recruitment and TLS formation." (PMID 37520560, 2023). "In addition, CXCL13 has been implicated in B cell and T cell infiltration into tumors and in anti-tumorigenic immune responses during immune checkpoint blockade in ovarian cancer and melanoma." (PMID 37035195, 2023). "TAP1 and CXCL13 were risk factors that affect the prognosis of ovarian cancer." (PMID 34631788, 2021). "In ovarian cancer, combination therapy with CXCL13 and an anti-PD-1 antibody inhibited tumor growth in a CXCR5+CD8+ T-cell expansion-dependent manner." (PMID 40406143, 2025). "In murine models of ovarian cancer, the exogenous administration of recombinant CXCL13 induced peritumoral TLSs, increased CD8+ T cell infiltration, and improved survival rates." (PMID 41029827, 2025). "For instance, in ovarian cancer, CXCL13 expression correlates with the presence of TLSs and favorable prognosis." (PMID 41029827, 2025). "For instance, recombinant CXCL13 promoted TLS formation and CD8+ T cell infiltration in ovarian cancer, and co‐injection of CXCL13 and CCL21 with gemcitabine significantly enhanced TLS formation in pancreatic cancer models." (PMID 40996881, 2025). "In a mouse ovarian cancer model, systemic delivery of CXCL13 successfully induced TLS formation and significantly improved survival by recruiting CD8+ T cells into the tumor." (PMID 41457151, 2025). "In the early phase of TLS development in ovarian cancer, CXCL13-producing CD4 T cells were predominantly coincident with CD4 and CD8 T cells, and it transmigrated away from T cell zones to the CD21+ FDCs as TLS matured in ovarian cancer." (PMID 39076974, 2024). "For instance, the CXCL13 induced synergy effect in anti-PD-1 therapy was observed only in subcutaneous ovarian cancer mouse model." (PMID 39569184, 2024). "In mouse HM-1 ovarian cancer models, the administration of recombinant CXCL13 was shown to induce TA-TLSs in both abdominal metastases and subcutaneous tumor, resulting in prolonged survival." (PMID 39569184, 2024). "Additional studies have shown that T cells in ovarian cancer can influence the recruitment of B cells through the secretion of CXCL13, an important B-cell chemoattractant." (PMID 39569184, 2024). "Administration of recombinant CXCL13 was reported to induce TA-TLSs and enhance survival in mouse ovarian cancer models." (PMID 39569184, 2024).
ovarian carcinoma (continued). "Up until now, investigations concerning CXCL13 within tumor contexts have been constrained to distinct types, like ovarian cancer." (PMID 38459390, 2024). "The literature also found that CXCL13 shapes an immunoreactive TME by facilitating the maintenance of CXCR5+CD8+ T cells in TLSs, and the combination of CXCL13 and anti-PD-1 significantly inhibited tumor growth in subcutaneous murine models of ovarian cancer." (PMID 38023214, 2023). "Univariate Cox analysis demonstrated that CXCL9, CXCL10, CXCL11, and CXCL13 were protective factors in ovarian cancer (HR < 1, p < 0.01)." (PMID 38054797, 2023). "The presence of CD4+ CXCL13+ T cells early in TLS formation in ovarian cancer also supports a role for these cells in co-ordinating adaptive immune responses and facilitating development of TLS to maximise their efficiency." (PMID 37520560, 2023). "They identified different immune cell subsets in samples from patients with high-grade ovarian cancer that were able to secrete CXCL13." (PMID 35053457, 2022). "In a mouse ovarian cancer model, recombinant CXCL13 induced TLS and enhanced survival by the infiltration of CD8+ T cells." (PMID 35552285, 2022). "Alternatively, we demonstrated that the injection of CXCL13 induced TLS formation accompanied by the inhibition of tumor growth in mouse models, and that CD4+ T cells were the major source of CXCL13 in human ovarian cancer TLS." (PMID 35552285, 2022). "Taken together, CXCL13 is a strong prognostic factor for ovarian cancer and is highly involved in the formation of TLS." (PMID 35552285, 2022). "CD8+ T cells producing CXCL13 were reported in lung cancer and ovarian cancer, whereas an analysis in nasopharyngeal cancer reported that most subsets of T cells producing CXCL13 were CD4+ T cells." (PMID 35552285, 2022). "We have found two immune-related genes, just TAP1 and CXCL13, which can be used as independent prognostic factors for ovarian cancer." (PMID 34631788, 2021). "Although the positive correlation between TAP1 and CXCL13 was weak in ovarian cancers according to the cBioPortal database, some studies still screened that they can be both used as prognostic markers of ovarian cancer." (PMID 34631788, 2021). "To date, some studies have shown the significance of TAP1 or CXCL13 as reliable immune-related prognostic genes in ovarian cancer." (PMID 34631788, 2021). "Meanwhile, TAP1 mRNA and CXCL13 mRNA levels were significantly elevated in ovarian cancer tissues compared to normal ones." (PMID 34631788, 2021). "In our study, we combined TMB and TIME evaluation methods to identify a set of genes related to the immune status of ovarian cancer, including CXCL13, FCRLA, MS4A1, and PLA2G2D." (PMID 34395521, 2021). "The CXCL13:CXCR5 axis has also been implicated in the initiation and progression of other solid tumors, such as ovarian cancer, melanoma, oral squamous cell carcinoma, osteosarcoma, thyroid cancer, and neuroblastoma." (PMID 31354634, 2019). "Our analysis shows that CXCL13 levels were significantly elevated in the sera of women with both early and late stage ovarian cancer, and the AUC values ranged from 0.71 (early stage) to 0.92 (late stage) when comparing cancer to healthy or benign samples." (PMID 29051715, 2017). "CXCL13 is also reported to serve as a positive prognostic indicator in ovarian cancer." (PMID 40607252, 2025). "In preclinical models of ovarian cancer, intraperitoneal injection of recombinant CXCL13 could induce TLS formation, then inhibit tumor progression and enhance the efficacy of anti-PD-1 therapy through increased infiltration of CXCR5+ CD8+ T cells." (PMID 40352278, 2025). "CD8+ T-cells and CD20+ B-cells were found to express CXCL13 in ovarian cancer." (PMID 38333212, 2024). "It has been confirmed that CXCL13 was contributed to TLSs formation in ovarian cancer." (PMID 38459390, 2024).